NT5C2 (5'-nucleotidase, cytosolic II)
Description:
Broad specificity cytosolic 5'-nucleotidase that catalyzes the dephosphorylation of 6-hydroxypurine nucleoside 5'-monophosphates. In addition, possesses a phosphotransferase activity by which it can transfer a phosphate from a donor nucleoside monophosphate to an acceptor nucleoside, preferably inosine, deoxyinosine and guanosine. Has the highest activities for IMP and GMP followed by dIMP, dGMP and XMP. Could also catalyze the transfer of phosphates from pyrimidine monophosphates but with lower efficiency. Through these activities regulates the purine nucleoside/nucleotide pools within the cell.
Synonyms: cN-II; NT5B; PNT5; GMP; SPG65; SPG45
Tractability: Small molecule: a structure with a bound ligand is known; it has a binding pocket of medium quality. PROTAC: ubiquitination databases record sites on it; its protein half-life has been measured.
Target class: Enzyme; Phosphatase
Safety:
Unwanted effects reported when the protein is acted on. In parentheses: how it was acted on, where the effect was seen, and who reports it.
noncirrhotic portal hypertension (source: ClinPGx)
Gene: Protein-coding gene on chromosome 10 (103,087,141 to 103,277,605, reverse strand). Ensembl gene ENSG00000076685.
Subcellular location: Cytoplasm, cytosol
Pathways (Reactome):
Drug ADME: Abacavir metabolism; Ribavirin ADME
Metabolism: Purine catabolism
Gene Ontology:
Molecular function: 5'-nucleotidase activity; ATP binding; identical protein binding; nucleoside phosphotransferase activity; protein binding; ubiquitin protein ligase activity; 5'-deoxynucleotidase activity
Biological process: allantoin metabolic process; dGMP metabolic process; GMP metabolic process; IMP catabolic process; IMP metabolic process; negative regulation of defense response to virus by host; protein K48-linked ubiquitination; purine ribonucleotide catabolic process; dGMP catabolic process
Cellular component: cytoplasm; cytosol
Genetic constraint (gnomAD): Loss-of-function variants: 25 observed, 30.95 expected, observed/expected ratio (o/e) 0.81, 90% interval 0.59 to 1.13. The upper end of that interval is the gene's LOEUF score, 1.13, which puts it in group 4 of 6, group 1 being the genes least tolerant of losing a copy. Missense variants: 247 observed, 378.26 expected, observed/expected ratio (o/e) 0.65, 90% interval 0.59 to 0.73. Synonymous variants: 131 observed, 133.55 expected, observed/expected ratio (o/e) 0.98, 90% interval 0.85 to 1.13.
Gene-disease validity (ClinGen):
ClinGen rates the evidence that NT5C2 causes each of these diseases.
complex hereditary spastic paraplegia (autosomal recessive): Definitive. A hereditary spastic paraplegia that is part of a larger syndrome.
Cancer hallmarks: escaping programmed cell death (promotes); proliferative signalling (promotes)
Homologues: Orthologues: macaque NT5C2 (100% identical), pig NT5C2 (99% identical), dog NT5C2 (99% identical), guinea pig NT5C2 (99% identical), mouse Nt5c2 (99% identical), rat Nt5c2 (99% identical), chimpanzee NT5C2 (97% identical), Drosophila melanogaster Nt5b (61% identical), Caenorhabditis elegans Y71H10B.1 (46% identical), Drosophila melanogaster Nt5c (23% identical). Paralogues in human: NT5DC4 (48% identical), NT5DC3 (26% identical), NT5DC2 (24% identical), NT5DC1 (19% identical).
Diseases named in the same sentence as NT5C2 in open-access papers:
NT5C2 is named in the same sentence as 63 diseases in open-access papers, as found by Europe PMC text mining. Sharing a sentence is not in itself a finding about the gene and the disease. The quoted sentences say what the papers report.
schizophrenia (18 papers, 2013 to 2026). A major psychotic disorder characterized by abnormalities in the perception or expression of reality. "Schizophrenia risk genotype is associated with reduced levels of both NT5C2 and ZNF804A in the developing brain, and a yeast two-hybrid screening suggests that their encoded proteins physically interact." (PMID 38279611, 2024). "The zinc finger protein 804A (ZNF804A) and the 5'-nucleotidase cytosolic II (NT5C2) genes are amongst the first schizophrenia susceptibility genes to have been identified in large-scale genome-wide association studies." (PMID 38279611, 2024). "The 5′-nucleotidase, cytosolic II gene (NT5C2, cN-II) encodes a phosphatase associated with disorders characterized by psychiatric and psychomotor disturbances, including schizophrenia 1, 2, 3, 4, Parkinson’s disease, and spastic paraplegia." (PMID 31097295, 2019). "We report altered cis‐regulation of BORCS7, AS3MT, and NT5C2 in association with schizophrenia risk variation, implicating these as genuine schizophrenia susceptibility genes at the locus." (PMID 27004590, 2016). "While not excluding effects on other genes in the region, this study implicates altered neural expression of BORCS7, AS3MT, and NT5C2 in susceptibility to schizophrenia arising from genetic variation at the chromosome 10q24 locus." (PMID 27004590, 2016). "Largest and most consistent effects were observed on BORCS7, AS3MT, and NT5C2, providing functional support for these as genuine susceptibility genes for schizophrenia." (PMID 27004590, 2016). "The identified interaction between ZNF804A/ZFP804A and NT5C2 suggests a shared biological pathway pertinent to schizophrenia susceptibility within a neuronal cell type thought to be central to the neurobiology of the disorder, providing a better understanding of its genetic landscape." (PMID 38279611, 2024). "Follow-up of the replicated SNVs in the literature and eQTL databases implicated some potentially interesting genes: NT5C2 is known to hydrolyse purine nucleotides and be involved in maintaining cellular nucleotide balance, and was previously associated with schizophrenia." (PMID 30617275, 2020). "Interestingly, two szDMPs (FDR < 0.2) in OLIG2+ are located within the regions reported to be associated with schizophrenia by GWAS including a CpG located in the intron of NT5C2 gene, involved in purine metabolism." (PMID 31288836, 2019). "The NT5C2 gene is implicated in risk for psychiatric and neurological conditions 1, 2, 3, 5, 6, and it has been recently classified as a high confidence schizophrenia risk gene by PsychENCODE, but the biological mechanisms responsible for these associations remain elusive." (PMID 31097295, 2019). "NT5C2 and CNNM2 are involved in etiology and pathogenesis of schizophrenia and have been confirmed as schizophrenia susceptibility genes." (PMID 34899152, 2021). "A meta-analysis of 18 GWASs for schizophrenia supported involvement of the MHC region, TCF4, POM121L2, NOTCH4, AS3MT, CNNM2, and NT5C2." (PMID 27064909, 2016). "Notably, ITIH3, ITIH4, and NT5C2 were selected for depression, while PSMA4 and ITSN1 were identified for schizophrenia." (PMID 38637810, 2024). "Unfortunately, in our sample sizes, there was no allelic association with schizophrenia for any of the five SNPs [rs7914558 (CNNM2), rs10503253 (CSMD1), rs7004633 (MMP16), rs11191580 (NT5C2) and rs12966547 (CCDC68)] (p > 0.22)." (PMID 24160291, 2013).
lung carcinoma (12 papers, 2007 to 2023). "Given that NT5C2 has been used as a prognostic marker in lung cancer, it is tempting to speculate that hMOB3s might be of clinical relevance in lung cancer." (PMID 31185650, 2019). "However, TK2 and NT5C2 were downregulated in lung cancer tissues." (PMID 32638267, 2020). "However, TK2 and NT5C2 were relatively downregulated in lung cancer tissues." (PMID 32638267, 2020). "In this cluster, NT5C2, API5, CPN, PRKAR1A and COPB1 were fully down-regulated in lung cancer." (PMID 23122428, 2012).
Hypertension (9 papers, 2018 to 2025). The presence of chronic increased pressure in the systemic arterial system. "NT5C2 encodes for a 5′ nucleotidase that functions in purine metabolism, and has a suggested role in type 2 diabetes and hypertension." (PMID 40182431, 2025). "In addition, AGTR1 and NT5C2 were associated with pre-hypertension (FDR = 3.53E−02), and AGTR1 and KCNC4 were associated with adverse events associated with cardiac arrhythmia (FDR = 3.59E−02)." (PMID 37210443, 2023). "The 5′-nucleotidase cytosolic II (NT5C2) variants were reported to be nominally associated with coronary heart disease (CHD) susceptibility in the subgroups of males and with hypertension and diabetes." (PMID 35592708, 2022). "We have also identified 8 important genes (NME4, PNPLA7, GGT5, PTGS2, IGF1R, NT5C2, ENTPD1 and PTEN), a number of gene ontology categories and biological pathways that may be associated with military pilot hypertension." (PMID 29996846, 2018). "We have also identified 8 important genes (NME4, PNPLA7, GGT5, PTGS2, IGF1R, NT5C2, ENTPD1 and PTEN), a few GO categories and biological pathways that may be associated with the military pilot hypertension." (PMID 29996846, 2018). "Targeting NT5C2 and PRCP appeared exclusively effective and safe for IA, including ischemic stroke and hypertension, which warranted future investigations." (PMID 40346920, 2025). "Targeting NT5C2 and PRCP appeared safe and exclusively effective for IA, including ischemic stroke and hypertension." (PMID 40346920, 2025). "The results from Western blotting showed that NME4 and PNPLA7 these two genes were up-regulated significantly and GGT5, PTGS2, IGF1R, NT5C2, ENTPD1 and PTEN these six genes were down-regulated significantly in PBMCs of military pilots with hypertension." (PMID 29996846, 2018).
Spastic paraplegia (7 papers, 2017 to 2025). Complete loss of the ability to move the lower limbs accompanied by spasticity of the lower limbs. "Importantly, NT5C2 mutations were reported to underlie recessive spastic paraplegia in a previous study; hence, NT5C2 was our best candidate." (PMID 28327087, 2017). "Most available literature regarding the human NT5C2 gene suggests that it has a dominant role in spastic paraplegia 45 (SPG45) and ALL." (PMID 32984406, 2020).
acute lymphoblastic leukemia (6 papers, 2016 to 2024). Leukemia with an acute onset, characterized by the presence of lymphoblasts in the bone marrow and the peripheral blood. "However, gain-of-function relapse-associated mutant forms of NT5C2 increase downstream purine secretion in acute lymphoblastic leukemia cells, including urate and xanthine." (PMID 39872146, 2024). "Whole-exome sequencing studies have recently revealed that somatic missense mutations in the gene encoding cN-II (NT5C2) are associated with relapsed acute lymphoblastic leukemia (ALL)." (PMID 27756303, 2016). "CRCD2, a first-in-class specific small molecule inhibitor of the cytosolic 5′ nucleotidase II (NT5C2), has been reported to be broadly active against NT5C2 in acute lymphoblastic leukemia (ALL)." (PMID 37532694, 2023). "A moderate increase of NT5C2 activity (two-five-fold) in ADF cells causes an increase of cell proliferation, while a strong increase of enzyme activity in acute lymphoblastic leukemia cells leads to nucleotide degradation and to an inhibition of proliferation." (PMID 33477638, 2021).
Obesity (6 papers, 2020 to 2025). Accumulation of substantial excess body fat. "For example, NT5C2, a purine-metabolizing enzyme, is ubiquitously expressed and has been associated with reduced adiposity, obesity, and obesity-related depression." (PMID 41006818, 2025). "On the other hand, higher NT5C2 expression positively correlates with obesity, which is in line with the lean phenotype observed in C. elegans after RNAi-driven knockdown of the ortholog gene Y71H10B." (PMID 34492009, 2021). "On the other hand, we found Nt5c2 expression to positively correlate with obesity traits in the mouse, which is in line with the knockdown of the C. elegans ortholog–Y71H10B." (PMID 34492009, 2021). "It will be very interesting to further investigate on these molecular mechanisms, since the knowledge of this matter will support the application of NT5C2 inhibitors not only in cancer but also in pathologies such as metabolic syndrome, obesity and diabetes." (PMID 33408634, 2020). "GCKR, ABCB11, CDKAL1, CDKN2B, NT5C2, and APOC1 were associated with metabolically unhealthy phenotypes in individuals with normal weight but not in those with obesity." (PMID 33500527, 2021). "GCKR, ABCB11, CDKAL1, CDKN2B, NT5C2, and APOC1 were associated with metabolically unhealthy in individuals with normal weight but not in those with obesity." (PMID 33500527, 2021). "He found GCKR, ABCB11, CDKAL1, CDKN2B, NT5C2, and APOC1 gene were associated with metabolically unhealthy phenotypes in individuals with normal weight but not in those with obesity, showing that certain genetic polymorphisms may also have an impact on the metabolic health in NWO populations." (PMID 39777912, 2025).
astrocytoma (4 papers, 2018 to 2023). "To demonstrate the dependence of NT5C2 activity on the oxidative state of the cell, we used an astrocytoma cell line, ADF, which, like several cancer cells, is well-equipped to counteract oxidative stress." (PMID 33477638, 2021). "In addition, the activity of NT5C2 was essential for survival in astrocytoma cells." (PMID 35047040, 2022).
hereditary spastic paraplegia (4 papers, 2017 to 2021). Hereditary spastic paraplegias (HSP) comprise a genetically and clinically heterogeneous group of neurodegenerative disorders characterized by progressive spasticity and hyperreflexia of the lower limbs. "Here, we describe the first exon rearrangement reported in the SPG45/SPG65 (NT5C2) loci in a family featuring a complex hereditary spastic paraplegias phenotype." (PMID 29123918, 2017).
leukemia (4 papers, 2016 to 2025). A malignant (clonal) hematologic disorder, involving hematopoietic stem cells and characterized by the presence of primitive or atypical myeloid or lymphoid cells in the bone marrow and the blood. "We propose that misregulation of purine nucleotidase may represent a common mechanism underlying chemoresistant leukemia driven by mutations in NT5C2." (PMID 27756303, 2016). "The mRNA amounts of the main nucleoside transporters (NT) and intracellular metabolizing enzymes (ME), hENT1, hENT2 (SLC29A2), hCNT1 (SLC28A1), hCNT2 (SLC28A2), hCNT3 (SLC28A3), DCK and cN-II (NT5C2), were measured in 50 pediatric leukemia cases by RQ-PCR." (PMID 27391351, 2016).
breast carcinoma (3 papers, 2017 to 2023). "Regarding the molecular subtypes of breast cancer, NT5C2 expression was significantly increased in patients with triple-negative breast cancer (TNBC) subtype, and reduced in patients with Luminal subtype." (PMID 36820551, 2023). "The results of the TIMER database showed that the expression of NT5C2, NT5DC1, and NT5DC3 were significantly downregulated in breast cancer tissues, while the expression of NT5DC2 were upregulated." (PMID 36820551, 2023). "There was a downregulation of NT5C2, NT5DC1, and NT5DC3 in breast cancer compared to normal tissues, and NT5DC2 instead." (PMID 36820551, 2023). "According to our study, the expression of NT5C2, NT5DC1, and NT5DC3 was downregulated, while the expression of NT5DC2 was upregulated in breast cancer tissues." (PMID 36820551, 2023).
glioblastoma (3 papers, 2015 to 2023). The most malignant astrocytic tumor (WHO grade IV). "In glioblastoma, NT5C2 could regulate tumor cell proliferation and drug sensitivity." (PMID 35047040, 2022).
Anxiety (2 papers, 2023 to 2026). Intense feelings of nervousness, tension, or panic often arise in response to interpersonal stresses. "Moreover, analysis of mouse phenotyping data revealed that whole-body Nt5c2 knockout alters locomotor activity, sensorimotor gating, and anxiety-related behaviors." (PMID 41495857, 2026). "Of the 11 gene scores in the anxiety symptom group, we replicated six genes, including CNNM2, EXD3, GBF1, NT5C2, NOLC1 and TRIM." (PMID 37322117, 2023).
multiple sclerosis (2 papers, 2022 to 2023). A progressive autoimmune disorder affecting the central nervous system resulting in demyelination. "In addition, NT5C2 is involved in metabolizing cladribine, an immunomodulatory drug used to treat multiple sclerosis." (PMID 37576396, 2023).
breast tumors (1 paper, 2023). "Likewise, both RT-qPCR quantified RNA and protein abundance of NT5C2 was significantly increased, but with significant suppression of PNP level in TC than TM area of breast tumors." (PMID 37532694, 2023).
epilepsy (1 paper, 2021). A brain disorder characterized by episodes of abnormally increased neuronal discharge resulting in transient episodes of sensory or motor neurological dysfunction, or psychic dysfunction. "Bioinformatics analysis revealed that the effects of AS3MT on epilepsy likely involved multiple targets including MTHFR, GSTM1, CYP17A1, NT5C2, YBX3, CNNM2, CACNB2, and TRIM26." (PMID 34899152, 2021). "The effects of AS3MT on epilepsy might involve multiple targets including CNNM2, CACNB2, TRIM26, MTHFR, GSTM1, CYP17A1, NT5C2, and YBX3." (PMID 34899152, 2021).
glioma (1 paper, 2020). A benign or malignant brain and spinal cord tumor that arises from glial cells (astrocytes, oligodendrocytes, ependymal cells). "Recurrent deletions in previously unknown glioma genes NT5C2, ADGRL2, and UIMC1 were observed whilst SUB1, CES1, and ITGA6 were frequently methylated in human LGGs; frequent CNVs in these genes were also present in human GBMs." (PMID 32727536, 2020).
Hyperglycemia (1 paper, 2021). An increased concentration of glucose in the blood. "Moreover, knockout of Nt5c2 (in mice) not only protects against high-fat diet-induced weight gain and adiposity but also improves insulin sensitivity and reduces hyperglycemia, all in line with our observation of improved healthspan and lifespan in C. elegans treated with RNAi against Y71H10B." (PMID 34492009, 2021).
hyperuricemia (1 paper, 2025). An abnormally high level of uric acid. "High plasma uric acid directly inhibits insulin signaling inducing insulin resistance, and we showed that NT5C2 deletion in mice lowered HFD-induced hyperuricemia." (PMID 39947478, 2025).
insomnia (1 paper, 2025). A sleep disorder characterized by difficulty in falling asleep and/or remaining asleep. "The results indicated that PRCP and NT5C2 might play crucial roles in IA formation, even in cases of aSAH, when compared to SBP, smoking, and insomnia." (PMID 40346920, 2025).
Insulin resistance (1 paper, 2025). Increased resistance towards insulin, that is, diminished effectiveness of insulin in reducing blood glucose levels. "We previously showed that cytosolic 5′-nucleotidase II (NT5C2)-deficient mice were protected against high-fat diet (HFD)-induced insulin resistance." (PMID 39947478, 2025). "However, we found that NT5C2-deficient mice were protected from HFD-induced weight gain, adiposity, insulin resistance, and hyperglycemia, with a possible implication of AMPK." (PMID 39947478, 2025).
malignant melanoma (1 paper, 2020). "Interestingly, activated cells cultured on patterned substrates show significantly higher expression of genes related to malignant melanoma such as CTGF (~5-fold) and NT5C2 (~3-fold) compared to cells cultured on non-patterned substrates." (PMID 32620903, 2020).